ROS1 (ROS proto-oncogene 1, receptor tyrosine kinase)
Diseases named in the same sentence as ROS1 in open-access papers (continued):
Sharing a sentence is not in itself a finding about the gene and the disease.
lung cancer (continued). "This panel, which was specifically designed for the detection of 63 known lung cancer-specific fusion genes, including ALK, RET, and ROS1 fusion genes, successfully identified SLC45A-ROS1 fusions in two patient samples." (PMID 38472960, 2024). "Given that ROS1-rearranged lung cancers often feature solid growth with signet ring cells or cribriform morphology with abundant extracellular mucus, these tumors may also present with calcifications similar to those observed in EGFR-mutated and ALK-rearranged lung cancers." (PMID 39391406, 2024). "Anaplastic lymphoma kinase (ALK), epidermal growth factor receptor (EGFR), ROS proto-oncogene 1 (ROS1), and serine/threonine-protein kinase B-Raf (BRAF) inhibitors have become key components of lung cancer therapy." (PMID 38785748, 2024). "Most patients with lung cancers harboring NTRK gene fusions exhibit clinical characteristics similar to those with ALK, RET, or ROS1 fusions, and are often found in a younger population with minimal or no smoking history." (PMID 39199653, 2024). "Crizotinib, an ATP-competitive small-molecule inhibitor of receptor tyrosine kinases C-Met, ALK, and ROS1, has shown significant efficacy in patients with advanced ALK-positive lung cancer." (PMID 36892747, 2023). "Lorlatinib, an orally administered inhibitor of anaplastic lymphoma kinase (ALK) and ROS1, was administered in patients with ALK rearrangement pursuant to the findings observed in lung cancer." (PMID 35953681, 2023). "Non‐small cell lung cancers with ERBB2 amplification, MET activation, KRAS G12C, RET, and ROS1 fusion resulted in the second‐highest frequency of recommendations." (PMID 36251535, 2023). "Historically, FISH has been used to identify gene fusion detection in clinical practice, as in the identification of ALK, ROS1, and RET rearrangements in lung cancer." (PMID 37143440, 2023). "In summary, this report confirms that MET amplification is a bona fide driver of ROS1 TKI resistance in ROS1-rearranged lung cancer and that a combination of CNS-penetrant and selective MET and ROS1 inhibitors can induce intra- and extracranial responses." (PMID 37923925, 2023). "The benefit of immunotherapy appears limited in most oncogene-addicted lung cancer subtypes, including ALK and ROS1 and potentially RET- and HER2-altered lung cancer." (PMID 38132389, 2023). "We utilized pentaplex panel testing for 23 lung carcinomas, 23 sarcomas, 4 thyroid carcinomas, 3 salivary gland tumors, and 3 pancreatic carcinomas with oncogenic gene translocations (ALK: 31; ROS1 10; RET: 9; NTRK1: 2; NTRK3: 4)." (PMID 37686416, 2023). "The immunohistochemistry (IHC) method is simple and cost-effective, and its use has been approved by the US FDA for the detection in lung cancer of ALK and ROS1 rearrangements." (PMID 36009413, 2022). "The prevalence of driver oncogenic alterations in patients with lung cancer, particularly EGFR, BRAF, HER2 and ROS1, was significantly higher in high exposure areas." (PMID 36208308, 2022). "Latest results have shown that around 83% of the lung cancer patients included in the cohort study (n = 2.204) were tested for EGFR, ALK, ROS-1, PD-L1 and / or BRAF." (PMID 35765059, 2022). "Similar findings have also been reported in other ROS1 and ALK lung cancer cohorts, further supporting the notion that ROS1‐rearranged and ALK‐rearranged NSCLCs are specifically associated with an elevated risk of thromboembolic events." (PMID 35510711, 2022). "Taking into account potential cancer type differences, we found that ROS1 (63% vs. 44%; Fisher’s exact test P < 0.0001) and ALK fusions (50% vs. 44%, Fisher’s exact test P = 0.006) remain more prevalent in female lung cancer patients." (PMID 36369474, 2022). "Sequentially, we evaluated the targetable variations detected ability in different samples, including EGFR, ALK, BRAF V600E, KRAS, MET ex14 skipping, RET, ROS1, ERBB2, which have high evidence in lung cancer." (PMID 36167530, 2022).
lung cancer (continued). "We found eight genes relevant to lung cancer (PDGFRB, RET, KRAS, KEAP1, ROS1, STK11, MET and ALK), for which integrating clinical data with our TME features clearly improves the ability to predict mutations in these genes." (PMID 36131239, 2022). "Lung cancer patients harboring therapeutically actionable fusion genes, such as ALK, RET, and ROS1, have experienced clinical benefits owing to the development of effective targeted therapies with crizotinib being foremost." (PMID 36081848, 2022). "A previous study in 36,813 Chinese lung cancer patients, focusing on eight key lung cancer driver genes (EGFR, ALK, MET, KRAS, ERBB2, ROS1, RET, and BRAF), revealed a prevalence of 0.03% for P/LP germline mutations." (PMID 35428225, 2022). "In line with previous reports, our analysis recapitulated the key targetable oncogenic fusion events in lung cancers, with a 4.2% frequency of ALK fusions, 1.3% of RET fusions, and 1.2% of ROS1 fusions." (PMID 36369474, 2022). "Genetic testing for advanced nonsmall cell lung cancer (NSCLC) includes EGFR, ALK, ROS1, BRAF, MET, HER-2, RET, NTRK1/2/3, PI3K, and PD-L1." (PMID 35368895, 2022). "The emergence of new lung cancer molecular subtypes of RET fusion type and ROS1 fusion type has brought new vitality to the establishment of a new molecular typing diagnosis and treatment model." (PMID 35433677, 2022). "Deregulation of PI3K/AKT signaling pathway in ALK-positive lung cancer was demonstrated by WES analysis, and significantly increased mRNA of ALK, ROS1, MET, SPP1 and PI3K signaling pathway was identified by NanoString assay." (PMID 34234236, 2021). "Lung cancer is the leading cause of cancer-related deaths in the world, and mutations and deregulation of many proteins and pathways, including EGFR, ALK, ROS1, and MET, play a significant role in lung cancer occurrence and development." (PMID 34603447, 2021). "Over the last several decades, clinical evaluation and treatment of lung cancers have largely improved with the classification of genetic drivers of the disease, such as EGFR, ALK, and ROS1." (PMID 33803619, 2021). "Analysis of the expression levels of common immune checkpoints (PD1 and PD‐L1 in our study) and lung cancer driver genes (ALK, EGFR, ROS1, and MET in our study) between two clusters revealed significant differences in PD1, PD‐L1, and MET gene expression." (PMID 34558724, 2021). "It was revealed that in lung cancer, SLC34A2 induces resistance to crizotinib when it undergoes molecular re-arrangement with ROS-1, a tyrosine kinase receptor." (PMID 34944522, 2021). "One such panel is the Ion Ampliseq RNA fusion lung cancer panel offered by ThermoFisher Scientific, Waltham, USA, which targets 70 known fusion transcripts of ALK, RET, ROS1, and NTRK." (PMID 34571741, 2021). "Pulmonary LELC had better prognosis, and previous studies also have discovered that classic lung cancer oncogenic drivers including KRAS, EGFR, BRAF, ALK, and ROS1 were limitedly involved in tumorigenesis and progression of pulmonary LELC." (PMID 34221995, 2021). "In patients in the advanced stages of lung cancer, finding target molecules, such as EGFR, ALK, and ROS1, is significant for making treatment decisions; as such, it is necessary to perform molecular testing at the time of initial diagnosis." (PMID 34441366, 2021). "ROS1 gene fusions were first identified in the human glioblastoma cell line U-118 MGROS1 and, subsequently, in lung cancer in 2007." (PMID 33435440, 2021). "Multiple oncogene fusions are currently targeted in lung cancer treatment, such as those involving ALK, RET, NTRK and ROS1 among many others." (PMID 34680187, 2021). "For lung cancer, we collect the status of the National Comprehensive Cancer Network (NCCN) recommended biomarkers: EGFR, ALK, BRAF, ROS1, KRAS, RET, NTRK and PD-L1." (PMID 33572220, 2021). "The Ampliseq RNA lung cancer panel, allowing the analysis of about 70 fusions involving ALK, ROS1, RET and NTRK1 is one of the most diffuse." (PMID 32726941, 2020).
lung cancer (continued). "Entrectinib received FDA approval for lung cancers harbouring ROS1 alteration in 2019, having demonstrated robust ALK and ROS1 inhibition, plus effective TRKA, TRKB and TRKC signalling suppression." (PMID 33172113, 2020). "ROS1-GOPC fusions are well known to be found in glioblastoma, cholangiocarcinoma, ovarian cancer, and non–small cell lung cancer." (PMID 32493317, 2020). "A previous study showed that targetable activating alterations in lung cancer genes, such as EGFR, ALK, RET and ROS1, are mutually exclusive molecular events." (PMID 32729257, 2020). "Specific tests to investigate the presence of ALK, ROS1 and RET rearrangements in lung cancer have been developed by Agena Bioscence." (PMID 32726941, 2020). "Crizotinib is a low molecular weight, orally available TKI that inhibits ROS1, MET and ALK and is considered the gold standard first-line treatment with demonstrated significant activity for lung cancers harbouring ROS1 gene rearrangements." (PMID 33172113, 2020). "This is consistent with other studies reporting low TMB in EGFR, ALK, ROS1, or RET-driven lung cancers [30•], but higher in KRAS or BRAF." (PMID 31172347, 2019). "The recent identification of driver oncogenes, such as EGFR, ALK, ROS1, and BRAF has already been successfully translated into clinical practice for individuals with lung cancer." (PMID 31142054, 2019). "Crizotinib, an ALK/ROS1/MET inhibitor, is highly effective against ROS1-rearranged lung cancer and is used in clinic." (PMID 31399568, 2019). "This is not surprising since these patients have acquired mutations during the course of the disease (EGFR T790 M) and the fact that this dataset includes fusions (ROS1, ALK in lung cancer, ABL1 in leukemia)." (PMID 29544535, 2018). "Given the prevalence of CCDC6 fusion to ROS1 and RET, this analysis will identify and tailor a treatment, with the aim to enhance the TKI efficacy and to prevent resistance in almost 1000 lung cancer patients." (PMID 29455670, 2018). "Few genes are recurrent partners in tyrosine kinase fusions in lung cancer, including CCDC6, a recurrent partner in ROS1 and RET fusions, that can be selected as possible target for new strategies of combined therapy including TKi." (PMID 29455670, 2018). "Recently, however, TK fusions have been identified involving ALK, ROS1 and RET kinases in 3–7, 1–2, and 0.7–2% of lung cancer, respectively." (PMID 29455670, 2018). "In this paper we utilized three transcriptome-based platforms and compared results with the gold standard of FISH testing for the detection of ALK, ROS1 and RET fusions in lung cancer." (PMID 28181564, 2017). "ALK, ROS1 and RET gene fusions are important predictive biomarkers for tyrosine kinase inhibitors in lung cancer." (PMID 28181564, 2017). "After that, several research groups have reported the presence of these fusions in patients who integrate a new molecular subset of lung cancer with similar characteristics to ALK-positive and ROS1-positive patients." (PMID 27528792, 2016). "GTx-186 and crizotinib inhibited the proliferation of HCC78 lung cancer cells, which harbors SLC34A2:ROS1 fusion and are dependent on ROS1 for growth, with an IC50 value of 293 nM and 495 nM, respectively." (PMID 24386191, 2013). "Activating ROS1 fusions (involving the FIG gene) were previously found in glioblastoma and more recently in lung cancer." (PMID 22140546, 2011). "In lung cancer, where actionable alterations such as EGFR, ALK, ROS1, and MET have direct therapeutic implications, optimizing patient selection for NGS testing could further enhance cost-efficiency." (PMID 41301039, 2025). "ALK, ROS1, RET, and NTRK1 fusions are observed frequently in lung cancer." (PMID 40223139, 2025). "The SEER database does not present molecular markers, including EGFR, ALK, and ROS1, which are critical in guiding the prognosis and therapy for lung cancer BM." (PMID 40098698, 2025).
lung cancer (continued). "In this scenario, customized medicine has brought successful outcomes in drug selection for lung cancer patients with NSCLC based on the paradigms of their molecular profiles, specifically those with positive genetic alterations in EGFR, ALK, ROS-1, HER2, BRAF, MET, and RET genes." (PMID 39410578, 2024). "As the most common fusion genes in lung cancer, ALK, RET, and ROS1 were selected for analysis." (PMID 38229122, 2024). "Here, we present a 10XGenomics scRNA-seq experiment, providing a controlled heterogeneous environment using lung cancer cell lines characterised by the expression of seven different driver genes (EGFR, ALK, MET, ERBB2, KRAS, BRAF, ROS1), leading to partially overlapping functional pathways." (PMID 38307867, 2024). "ROS1-rearranged lung cancer is more frequently observed in women, non-smokers, and younger individuals compared to other types of lung adenocarcinoma." (PMID 39391406, 2024). "Few reports exist on lung cancer with extensive calcified lesions, and no cases have documented ROS1 fusions with such extensive calcification." (PMID 39391406, 2024). "In this case, the NRAS mutation was predominantly identified, the most common gene mutations in lung cancer are all negative, including EGFR, KRAS, BRAF, ALK, ROS1, and so on." (PMID 39507527, 2024). "The main targeted treatments approved for lung cancer with ROS1 rearrangement include drugs such as Crizotinib, a tyrosine kinase inhibitor initially approved for ALK-positive patients, which has shown significant efficacy in ROS1-positive patients as well." (PMID 39199653, 2024). "One of the lung cancer brain metastases samples has been examined without rearrangements of ALK and ROS1 and EGFR mutation." (PMID 37479733, 2023). "Thus, we conducted a correlation study between FGF11 and EGFR (19DEL, L858R), EGFR (Exon 20ins), KRAS (G12C), ALK, ROS1, BRAF, NTRK1/2/3, MET, and RET, which are all recommended by the NCCN guidelines for the diagnosis of nonsmall cell lung cancer." (PMID 37250453, 2023). "Both curation techniques found that lung cancer patients with a positive biomarker result for ROS1 lived longer than patients with a negative result." (PMID 36980739, 2023). "In all, 8398 (98%) were adults and 195 (2%) were children; 7865 patients (92%) were treated for lung cancer, of whom 7270 (92%) had an ALK rearrangement, 290 (4%) had an ROS1 rearrangement and 305 (4%) had another molecular abnormality, such as in RET, MET, or NTRK." (PMID 37894307, 2023). "Notably, KRAS, BRAF, ERBB2, PIK3CA, RET, ROS1, ALK, and NRTK1/2/3 have been proposed as prognostic markers, making substantial contributions to genotype-directed therapies for advanced lung cancer." (PMID 36619227, 2023). "None of the 1293 lung carcinomas with driver alterations in EGFR/ALK/ROS1/RET/MET oncogenes had NTRK 5′/3′-end expression imbalances." (PMID 37762506, 2023). "The responsiveness in two lung cancers without ROS1 translocation to crizotinib also led to no statistical significance between NSCLCs with and without ROS1 translocation." (PMID 35628598, 2022). "While our retrospective biomarker analysis was fairly comprehensive, it is limited due to several factors, including that many lung cancers were diagnosed before molecular testing for biomarkers, such as EGFR, ALK, ROS1 and others, were considered standard of care." (PMID 35805276, 2022). "While somatic mutations of EGFR, BRAF, HER2, MET and chromosomal rearrangements of ALK, ROS1, RET are responsible for lung cancer, risk factors for these genomic alterations have not yet been identified." (PMID 36208308, 2022). "Known ALK/ROS1 fusions and 5’‐/3’‐end mRNA unbalanced expression were analyzed in 2009 EGFR mutation‐negative non‐small cell lung cancer (NSCLC) samples." (PMID 35322575, 2022).
lung cancer (continued). "However, in the future, 10% of patients with non-smoking NSCLC should be included in different molecular studies, which will show that NSCLC’s origin is more significant than the already known oncogenic drivers of lung cancer, such as EGFR, ALK, or ROS1." (PMID 35203569, 2022). "Interestingly, our results showed that the risk of VTE in ROS1 rearrangements(ROS1+) patients is 2.63-fold greater than that in ROS1- patients, and the odds of VTE in ROS1+ lung cancer were higher than ALK+, EGFR+ and KRAS+ cohorts in the univariate analysis." (PMID 36300098, 2022). "Known ALK/ROS1 fusions and 5′‐/3′‐end unbalanced expression were analyzed in 2009 EGFR mutation‐negative non‐small cell lung cancer (NSCLC) samples with RT‐PCR tests, which were optimized for the use with FFPE‐derived RNA." (PMID 35322575, 2022). "KRAS, ROS1, ALK, and EGFR are the main biomarkers affecting clinical practice of lung cancer." (PMID 36260870, 2022). "We further analyzed mRNA expression of 67 genes in 5 ALK-positive lung cancer samples and the corresponding pericarcinous (normal) tissues by NanoString assay, and found increased mRNA of ALK, ROS1, MET, SPP1 and PI3K signaling pathway in ALK-positive lung cancer." (PMID 34234236, 2021). "Finally, we detail the current landscape of additional actionable alterations (EGFR, ALK, ROS1, MET) in lung cancer, a biomarker-rich malignancy that has greatly benefitted from the precision oncology revolution." (PMID 34198738, 2021). "Additionally, gilteritinib also displayed potency against ROS1 fusion gene-expressing lung cancer cell lines (HCC78 cells harbor SLC34A2-ROS1 and JFCR-168 harbor CD74-ROS1) and significant tumor regression was observed in vivo." (PMID 33627640, 2021). "Interestingly, we found increased mRNA of ROS1 and MET in ALK-positive lung cancer, the molecular mechanism is unclear at present." (PMID 34234236, 2021). "Metastases affecting the CNS are commonly observed in patients with lung cancer and ROS1-positive cancer patients are no exception." (PMID 33172113, 2020). "We provide specific and previously undescribed data on fusions involving RAF1, ROS1, and BRD4 that suggest that existing drugs could be repurposed for use in rare pancreatic, breast, and lung cancers." (PMID 31097696, 2019). "This may lead to an ultra-sensitive method to detect and culture circulating CTCs in blood or in cellblocks, which could further be used for immunohistochemistry analysis of the lung cancer biomarkers p40, TTF1, ALK, ROS1, and PD-L1." (PMID 30891428, 2019). "We therefore examined ROS1 expression at the C-terminus in 37 lung cancer cell lines with or without ROS1 fusion." (PMID 30943926, 2019). "Indeed we have observed in case reports that non-responding metastatic do not have molecular expression of the primary site (EGFR, ALK, ROS1, ALK or PD-L1) or there are cases where we have a different lung cancer or lung cancer transformation 34-36." (PMID 31598145, 2019). "We also speculate on the role of CCDC6 as common partner of at least two TK, ROS1 and RET, for its targeting in combined therapies including TKIs in lung cancer treatment." (PMID 29455670, 2018). "Similarly to the other lung cancer gene fusions, we firstly reported NRG1 rearrangement patterns in form of isolated 3′ signals, thus indicating a strength analogy with ALK and ROS1 fusions, where a 5′ gene deletion was frequently observed." (PMID 29515761, 2018). "Also the prevalence of the RET fusions greatly increases (from a median 1.8% to a significative 6.3%) when evaluated in 159 lung cancer patients wild type for EGFR, ALK, ROS1, BRAF, KRAS, HER2." (PMID 29455670, 2018). "This review summarizes the hot topics of immunohistochemistry in lung cancer, including (i) adenocarcinoma vs squamous cell carcinoma; (ii) neuroendocrine markers; (iii) ALK, ROS1, and EGFR; (iv) PD-L1 (CD274); (v) lung carcinoma vs malignant mesothelioma; and (vi) NUT carcinoma." (PMID 29538329, 2018).